MBD2 (methyl-CpG binding domain protein 2)
Diseases named in the same sentence as MBD2 in open-access papers (continued):
Sharing a sentence is not in itself a finding about the gene and the disease.
tumor (48 papers, 2001 to 2025). "Compared to other MBPs, Mbd2 shows a relatively greater affinity for methylated DNA in the promoter regions of several tumor suppressor genes, causing their transcriptional repression." (PMID 38556549, 2024). "In the present study, we performed studies in human patients and animal models to elaborate the impact of MBD2, a reader for interpretation of DNA methylome-encoded information, on tumor metastasis." (PMID 37142578, 2023). "We demonstrated evidence suggesting an association between MBD2 expression and tumor metastasis in LUAD patients." (PMID 37142578, 2023). "PRMT5 is also important in MBD2–NuRD-associated gene silencing in tumor cells through PRMT5-mediated symmetric methylation of histone arginine residues and is associated with MBD2a but not MBD2b in HeLa cell extracts." (PMID 37307480, 2023). "Analysis of TNBC patient datasets reveals high tumor expression of the epigenetic reader methyl-CpG-binding domain protein 2 (MBD2), specifically the alternative splicing variant 2 (MBD2_v2) expression and high relapse rate and high BMI." (PMID 33339340, 2020). "Here we examine how the increased inflammatory response and tumour suppression phenotype interact in the Mbd2‐deficient mouse intestine." (PMID 29603746, 2018). "In our mouse model, the inflammation can override the Mbd2‐deficient‐dependent anti‐tumour suppression mechanism to such an extent that Apc+/minMbd2−/− mice develop adenocarcinomas, which are rarely, if ever, seen in this model without an inflammatory insult." (PMID 29603746, 2018). "Potentially, in the early stages, the acute Th1–Ifng inflammatory response in the Mbd2−/− mouse is associated with tumour clearance." (PMID 29603746, 2018). "In prostate cancer cells, loss of MBD2 suppresses tumor growth through hypermethylation and silencing of pro-metastatic genes." (PMID 27303433, 2016). "More patients are needed to verify the association of MBD2 and tumor metastasis." (PMID 37142578, 2023). "The methyl-CpG-binding domain 2 (MBD2), a “reader” to interpret DNA methylome-encoded information, has been noted to be involved in the development of certain types of tumors, while its exact impact on tumor metastasis remains elusive." (PMID 37142578, 2023). "As a proliferative disease comparable to tumors, PH may also be influenced by multiple tumor-associated genes, including MBD2." (PMID 35785161, 2022). "hTERT is usually hypermethylated and silenced, but is expressed in most cancer cells and therefore, in regards to this mechanism, loss of MBD2 may encourage tumor growth." (PMID 27303433, 2016). "It has been demonstrated that these inhibitors lead to a reduction in MBD2 levels and the inhibition of tumor formation in human tumor xenografts in nude mice." (PMID 40533455, 2025). "We then measured the total weight of the excised tumors of the mice sacrificed before or at postnatal week 20 and found a significant reduction in tumor weight in the Mbd2-KO group compared to the wild-type group." (PMID 38556549, 2024). "Based on the liver specimen and hematoxylin and eosin (HE) staining results, MBD2 + Vehicle mice presented a greater tumor load than Vector + Vehicle mice did." (PMID 39350229, 2024). "Previously, Mbd2 was suggested to promote tumor growth and metastasis; however, past studies were performed in cancer cell lines and xenografts in immunocompromised mice and used either antisense oligonucleotide- or siRNA-mediated knockdown approaches." (PMID 38556549, 2024). "Methyl‐CpG‐binding domain 2 (MBD2) attaches to methylated DNA, which mediates methylated gene transcription, leading to gene silencing and affecting tumor progression." (PMID 39676597, 2024).
tumor (continued). "Our results demonstrated that deletion of Mbd2 in PyMT mice impedes primary tumor growth and lung metastasis at the experimental endpoint (postnatal week 20)." (PMID 38556549, 2024). "It is plausible that tumor cells utilize the TGF-β1-SMAD3 pathway to increase Mbd2 expression, which in turn drives the transcription of genes involved in metastasis." (PMID 38556549, 2024). "Previous studies have also reported the use of gene editing techniques to study the function of MBD2, but most of them focused on its role in tumor cells." (PMID 39198853, 2024). "Owing to the heavy tumor burden, the MBD2 + Vehicle group had a greater liver-to-body weight ratio than did the Vector + Vehicle group." (PMID 39350229, 2024). "Taken together, the results of this study elucidate the potential mechanism underlying the overexpression of MBD2 in CCA and its contributions to tumor progression and chemoresistance." (PMID 39350229, 2024). "Mechanistically, MBD2 selectively bound to the methylated CpG DNA within the DDB2 promoter, by which MBD2 repressed DDB2 expression to promote tumor metastasis." (PMID 37142578, 2023). "As a result, administration of MBD2 siRNA-loaded liposomes remarkably suppressed EMT along with attenuated tumor metastasis in the B16F10 tumor-bearing mice." (PMID 37142578, 2023). "GO enrichment analysis characterized top 10 terms enriched with the differential expressed genes (DEGs) which involved in cell morphogenesis, adhesion and migration, indicating a pivotal role of MBD2 in tumor metastasis." (PMID 37142578, 2023). "Collectively, these data support that MBD2 is likely involved in tumor metastasis during the course of LUAD progression." (PMID 37142578, 2023). "Collectively, our data support that MBD2 promotes tumor metastasis by enhancing EMT via attenuating DDB2 expression." (PMID 37142578, 2023). "In the current report, we focused on the role of MBD2 in pathogenesis of tumor metastasis, particularly in the metastasis of LUAD, as metastasis is one of the most important hallmarks of LUAD." (PMID 37142578, 2023). "Taken together, our data support that MBD2 enhances EMT, by which it promotes cancer cell migration and invasion predisposing to tumor metastasis." (PMID 37142578, 2023). "Mechanistically, MBD2 selectively binds to the methylated CpG DNA within the DDB2 promoter, by which it represses DDB2 expression predisposing to tumor metastasis." (PMID 37142578, 2023). "Nevertheless, regardless of which point of view is more persuasive, all of these findings suggest the implication of MBD2 in modulating tumor metastasis, thereby contributing to the pathogenesis of cancer progression." (PMID 37142578, 2023). "As a result, liposomes loaded with MBD2 siRNA suppressed tumor metastasis in a B16F10 tumor-bearing mouse model." (PMID 37142578, 2023). "Further investigation illustrated that DNMT1/3A/3B, TDG, SMUG1, UNG, NEIL1, MDB3/4, ZBTB33, and UHRF1/2 were essentially upregulated in tumor samples, while TET2, MBD1, and MBD2 were downregulated in tumor samples." (PMID 35205097, 2022). "MBD2 mediates epigenetic transcriptional silencing by binding to methylated DNA, thus playing an important role in preventing tumor‐promoting inflammation." (PMID 35051313, 2022). "Our study found that the high level of MBD2 in tumor and adjacent tissue predicted a favorable RFS, indicating the variant of MBD2 is likely to be MBD2c." (PMID 35051313, 2022). "Our previous study also showed that MBD2 acts as a tumor suppressor in T cell acute lymphoblastic leukemia (T-ALL) lymphomagenesis in murine experiments." (PMID 34789717, 2021). "As we previously identified upregulation of Lect2 the tumour suppression observed in the ApcMin/+Mbd2−/− we generated ApcMin/+Mbd2−/−Lect2−/− to clarify its role in this phenotype." (PMID 30559928, 2018). "Combining models revealed that prior to inflammation the altered Mbd2−/− immune response plays a role in intestinal tumour suppression." (PMID 29603746, 2018).
tumor (continued). "We next sought to establish the effect of the Mbd2−/− inflammatory response on the tumour suppression observed in the Apc+/minMbd2−/− intestine." (PMID 29603746, 2018). "To summarise, in the intestine the normal function of Mbd2 is exploited by cancer cells to enable tumourigenesis, while in the immune system it plays a key role in preventing tumour‐enabling inflammation." (PMID 29603746, 2018). "Using the colon tissues from these tumor rats, the microarray and real-time PCR results both showed that colon Mbd2 was expressed higher in the S.LEW congenic strain compared with S." (PMID 27073989, 2016). "mbd2−/− mice exhibit hypermethylation of certain tumor suppressor genes which is partial in mbd2−/+ mice." (PMID 24204564, 2013). "Several studies have demonstrated altered MBD2 mRNA expression in various tumour tissue specimens, but the findings have been inconsistent." (PMID 18414412, 2008). "Compared to the adjacent normal tissue, a significant decrease in MBD2 mRNA expression has been observed in various tumour tissue types." (PMID 18414412, 2008). "In this study, we measured the mRNA expression level of three methylation-related genes (DNMT1, DNMT3b and MBD2) in NSCLC tumour tissues using quantitative real-time PCR and evaluated their prognostic values." (PMID 18414412, 2008). "This is because overexpression of MBD2 during gliomagenesis may inhibit the antiangiogenic activity of a key tumour suppressor, thereby promoting tumour growth." (PMID 39800672, 2025). "MBD2 was also shown to facilitate tumor metastasis by mitigating DDB2 expression." (PMID 41258082, 2025). "Methyl‐CpG‐binding domain 2 (MBD2) performs a crucial role in tumor progression." (PMID 39676597, 2024). "PyMT upregulates Mbd2, and upregulation of Mbd2 precedes the appearance of measurable primary tumors, consistent with the idea that Mbd2 partially mediates the effects of PyMT on cellular pathways that drive tumor progression; specifically, Mbd2 deletion inhibits the activation of these pathways." (PMID 38556549, 2024). "In addition to tumor progression, lung metastasis is significantly reduced upon genetic ablation of the Mbd2 gene." (PMID 38556549, 2024). "The late appearance of tumors in Mbd2−/− mice might be a consequence of slowed tumor growth; therefore, tumors may reach a detectable size later in these mice." (PMID 38556549, 2024). "In conclusion, our study strengthens the link between MBD2 and HNSCC, highlights its high expression in tumor tissues and association with poor prognosis and may be an independent prognostic factor for HNSCC patients." (PMID 39676597, 2024). "Together, our data support that MBD2 could be a promising prognostic marker for tumor metastasis, while strategies aimed at silencing MBD2 with siRNA-loaded liposomes could be a viable approach against tumor metastasis in clinical settings." (PMID 37142578, 2023). "We speculated that the expression of MBD2 induced by TGF-β1 might be depended on the canonical SMAD pathway in tumor cells as well, but it needs to be confirmed." (PMID 37142578, 2023). "Interestingly, the damaged DNA binding 2 (DDB2), a well-known and potent inhibitor for tumor metastasis, was characterized in the cluster of genes whose expression was upregulated in the MBD2 siRNA transfected cells." (PMID 37142578, 2023). "However, in contrast to our observation, Pei and colleagues reported that lower MBD2 expression was significantly correlated with higher tumor stage and metastasis via deteriorating the EMT process." (PMID 37142578, 2023).
tumor (continued). "Collectively, our study indicates that MBD2 could be a promising prognostic marker for tumor metastasis, while administration of MBD2 siRNA-loaded liposomes could be a viable therapeutic approach against tumor metastasis in clinical settings." (PMID 37142578, 2023). "Together, our data not only provide novel insights into the pathogenesis underlying tumor metastasis, but also demonstrate evidence supporting that MBD2 siRNA liposomes could be a viable approach against tumor metastasis in clinical settings." (PMID 37142578, 2023). "Indeed, MBD2 has been shown to inhibit aberrantly methylated tumor suppressive genes by binding to the methylated CpG DNA within the promoter regions." (PMID 37142578, 2023). "Third, the expression of MBD2 may facilitate tumor growth, as evidenced by the significantly lower tumor volume, size and mass in the L-MBD2 siRNA treated mice." (PMID 37142578, 2023). "Third, owing to the vital role of MBD2 in tumor immunity, we additionally investigated whether its expression could predict the efficacy and prognosis of immunotherapy." (PMID 36276973, 2022). "The overall survival time (OS) of the MBD2 low expression group was better than that of the high expression group, suggesting that DNA methylation-related genes are closely related to the tumor immune microenvironment." (PMID 35814273, 2022). "Previous data have suggested that MBD2 silences key tumor suppressors that might influence tumoral stemness in several cancers." (PMID 34789717, 2021). "The MBD2-NuRD (Nucleosome Remodeling and Deacetylase) complex is an epigenetic reader of DNA methylation that regulates genes involved in normal development and neoplastic diseases." (PMID 25753662, 2015). "In this study, we measured the mRNA expression levels of three methylation-regulating genes (DNMT1, DNMT3b, and MBD2) in 148 tumour samples from patients with non-small cell lung cancer (NSCLC) using quantitative real-time polymerase chain reaction and then determined their prognostic values." (PMID 18414412, 2008). "Therefore, we next checked whether the expression of forkhead box P3 (Foxp3), a marker for regulatory T cells (Tregs), which suppress the immune response, was altered in formalin-fixed primary tumor tissues obtained from wild-type and Mbd2-deleted PyMT mice." (PMID 38556549, 2024). "Therefore, administration of liposomes carrying MBD2 siRNA suppressed tumor metastasis in the lung." (PMID 37142578, 2023). "Indeed, altered MBD2 expression has been consistently noted to impact tumorigenesis on mouse cancer cell lines and on human cancer cell xenograft models, but its impact on tumor metastasis is yet to be elucidated." (PMID 37142578, 2023). "Also, ethyl-CpG-binding domain protein 2 (MBD2) may play a role in the tumor initiation capacity in inoculated TNBC cell lines." (PMID 35406618, 2022). "Thus, Mbd2 function may play a significant role in the progression from a protective acute response to a chronic tumour‐promoting environment." (PMID 29603746, 2018). "However, the additional loss of Lect2 failed to reverse the suppression of tumour initiation observed in the ApcMin/+Mbd2−/− mice indicating Lect2 does not play a significant role in the suppression of intestinal tumourigenesis observed in that model." (PMID 30559928, 2018). "However, MBD2-TRD linked by the fusion part of the Gal4 DNA binding domain to the Gal4 sequence had a variable effect on the particular promoters and in the different tumour cells." (PMID 20565761, 2010).
tumor (continued). "This study sought to assess the clinical relevance of MBD2 expression in HNSCC, with a particular focus on elucidating its functional role in tumor progression and its regulatory influence on p21 expression and cellular proliferation." (PMID 39676597, 2024). "Conversely, some well-known factors related to tumor growth promotion, such as HMGA1, GTF3A, PHF19, CENPX, and MBD2, were upregulated." (PMID 35935940, 2022). "In the 20 cases analyzed, we detected three fusion events in known cancer driver genes (ATM in LUSC2; PTEN in LUSC1; WHSC1 in LUSC1), and a further seven events in candidate tumor-suppressor genes, including BOD1, DLG2, MBD2, and RBL1." (PMID 30348992, 2019). "First, we observed that MBD2 expression in tumors was not correlated with sex, smoking history, or the degree of tumor differentiation." (PMID 37142578, 2023). "Mechanistically, MBD2 selectively bound to the methylated CpG DNA within the damage-specific DNA binding protein 2 (DDB2) promoter, by which it repressed DDB2 expression to enhance EMT process, thereby leading to tumor metastasis." (PMID 37142578, 2023). "Moreover, in vitro studies corroborated that MBD2 is involved in the regulation of TGF-β1-induced migration, invasion and EMT in multiple types of tumor cells." (PMID 37142578, 2023). "Indeed, intratracheal instillation of liposomes carrying MBD2 siRNA substantially inhibited tumor growth and metastasis in a B16F10 tumor-bearing animal model." (PMID 37142578, 2023). "Thus, the role of Mbd2 in controlling the CD4 and Ifng immune response is likely to be of great interest because ‘tumour‐promoting inflammation’ is now identified as an enabling characteristic in the hallmarks of cancer." (PMID 29603746, 2018). "Except for few being chromatin regulators (CGBP, MBD2, and DNMT1), all of these TFs were found to have tumor suppressor functionality (BRCA1, E2F1&2&5&7, EGR1-4, FLI1, NRF1, TFDP2, and STAT1), or indirectly mediate the suppression of tumorigenesis and tumor suppressor activity (SP4 and ZBTB33)." (PMID 29740534, 2018). "Mbd2 might not be the major player in tumorigenesis, as tumor appearance is delayed but still occurs in KO mice." (PMID 38556549, 2024). "Mechanistically, circKCNN2 sponges miR-520c-3p, avoiding its binding to MBD2 (methyl-DNA-binding domain protein 2) and thus resulting in reduced proliferation, migration, colony formation, and cell cycle progression in HCC cells and a lower tumor burden in vivo." (PMID 38398157, 2024). "Taken together, these results support that the liposome-based MBD2 siRNA antagonizes TGF-β1-induced cancer cell migration, invasion coupled with attenuated EMT, and therefore, it could be a viable therapeutic approach against tumor metastasis." (PMID 37142578, 2023). "In consideration of the MBD2 expression were highly correlated to immune cells quantity, especially for activated CD4+ and CD8+ T-cells, as well as its preferable prognostic value, we next thoroughly analyzed the role of MBD2 in tumor immune environment formation." (PMID 36276973, 2022). "Potentially, this attenuation of tumourigenesis is due to a lack of Mbd2‐dependent silencing of tumour suppressor genes; however, the mechanism of Apc+/minMbd2−/− tumour suppression remains unknown." (PMID 29603746, 2018). "In the present study, NSCLC tumour tissues had significantly lower levels of MBD2 expression than did adjacent normal tissues (data not shown), suggesting that the effect of MBD2 expression on clinical outcome may be related to demethylation." (PMID 18414412, 2008). "We can hypothesise that the absence of MBD2 produces a ‘leak’ in the CpG island hypermethylation silencing of tumour-suppressor genes, thereby partially aborting aberrant cancer growth." (PMID 16404435, 2006). "Therefore, MBD2 could be a viable target against tumor metastasis without discernable side effect." (PMID 37142578, 2023).